SUPT4H1 (SPT4 homolog, DSIF elongation factor subunit)
Description:
Component of the DRB sensitivity-inducing factor complex (DSIF complex), which regulates mRNA processing and transcription elongation by RNA polymerase II. DSIF positively regulates mRNA capping by stimulating the mRNA guanylyltransferase activity of RNGTT/CAP1A. DSIF also acts cooperatively with the negative elongation factor complex (NELF complex) to enhance transcriptional pausing at sites proximal to the promoter. Transcriptional pausing may facilitate the assembly of an elongation competent RNA polymerase II complex. DSIF and NELF promote pausing by inhibition of the transcription elongation factor TFIIS/S-II. TFIIS/S-II binds to RNA polymerase II at transcription pause sites and stimulates the weak intrinsic nuclease activity of the enzyme. Cleavage of blocked transcripts by RNA polymerase II promotes the resumption of transcription from the new 3' terminus and may allow repeated attempts at transcription through natural pause sites. DSIF can also positively regulate transcriptional elongation and is required for the efficient activation of transcriptional elongation by the HIV-1 nuclear transcriptional activator, Tat. DSIF acts to suppress transcriptional pausing in transcripts derived from the HIV-1 LTR and blocks premature release of HIV-1 transcripts at terminator sequences.
Synonyms: SPT4H; SUPT4H; Spt4; Supt4a
Tractability: Small molecule: a structure with a bound ligand is known. PROTAC: UniProt records ubiquitination sites on it; ubiquitination databases record sites on it; its protein half-life has been measured.
Gene: Protein-coding gene on chromosome 17 (58,345,175 to 58,353,093, reverse strand). Ensembl gene ENSG00000213246.
Subcellular location: Nucleus
Subcellular location (Human Protein Atlas): Nucleoplasm
Pathways (Reactome):
Disease: Abortive elongation of HIV-1 transcript in the absence of Tat; Formation of HIV elongation complex in the absence of HIV Tat; Formation of HIV-1 elongation complex containing HIV-1 Tat; Formation of the HIV-1 Early Elongation Complex; HIV elongation arrest and recovery; Pausing and recovery of HIV elongation; Pausing and recovery of Tat-mediated HIV elongation; Tat-mediated HIV elongation arrest and recovery; Tat-mediated elongation of the HIV-1 transcript
Gene expression (Transcription): Formation of RNA Pol II elongation complex; Formation of the Early Elongation Complex; RNA Polymerase II Pre-transcription Events; RNA Polymerase II Transcription Elongation; RNA polymerase II transcribes snRNA genes
Gene Ontology:
Molecular function: protein binding; protein heterodimerization activity; RNA polymerase inhibitor activity; RNA polymerase II complex binding; zinc ion binding
Biological process: negative regulation of DNA-templated transcription, elongation; negative regulation of transcription by RNA polymerase II; positive regulation of DNA-templated transcription, elongation; positive regulation of transcription by RNA polymerase II; transcription elongation by RNA polymerase II; transcription pausing by RNA polymerase II; regulation of DNA-templated transcription; transcription elongation-coupled chromatin remodeling
Cellular component: DSIF complex; nucleus; nucleoplasm
Genetic constraint (gnomAD): Loss-of-function variants: 11 observed, 17.37 expected, observed/expected ratio (o/e) 0.63, 90% interval 0.4 to 1.05. The upper end of that interval is the gene's LOEUF score, 1.05, which puts it in group 4 of 6, group 1 being the genes least tolerant of losing a copy. Missense variants: 102 observed, 146.23 expected, observed/expected ratio (o/e) 0.7, 90% interval 0.59 to 0.82. Synonymous variants: 57 observed, 58.11 expected, observed/expected ratio (o/e) 0.98, 90% interval 0.79 to 1.22.
Homologues: Orthologues: chimpanzee SUPT4H1 (100% identical), dog SUPT4H1 (100% identical), guinea pig SUPT4H1 (100% identical), macaque SUPT4H1 (100% identical), mouse Supt4a (100% identical), pig SUPT4H1 (100% identical), rabbit SUPT4H1 (100% identical), rat Supt4h1 (100% identical), tropical clawed frog supt4h1 (96% identical), zebrafish supt4h1 (88% identical), Drosophila melanogaster spt4 (60% identical), Caenorhabditis elegans spt-4 (55% identical).
Diseases named in the same sentence as SUPT4H1 in open-access papers:
SUPT4H1 is named in the same sentence as 13 diseases in open-access papers, as found by Europe PMC text mining. Sharing a sentence is not in itself a finding about the gene and the disease. The quoted sentences say what the papers report.
Huntington disease (7 papers, 2015 to 2025). Huntington disease (HD) is a rare neurodegenerative disorder of the central nervous system characterized by unwanted choreatic movements, behavioral and psychiatric disturbances and dementia. "Moreover, a recent study indicated that the transplantation with neural precursor cells derived from SUPT4H1 gene-edited iPS cells exhibited promising therapeutic effects in a mouse model for Huntington’s disease." (PMID 39285205, 2024).
colorectal cancer (1 paper, 2016). A primary or metastatic malignant neoplasm that affects the colon or rectum. "Among these, a chimeric transcript resulting from the fusion of RNF43 and SUPT4H1 was found to occur frequently in primary colorectal carcinoma." (PMID 27461012, 2016).
cancer (4 papers, 2016 to 2021). A tumor composed of atypical neoplastic, often pleomorphic cells that invade other tissues. "Also, we found an alternative fusion transcript in the primary carcinoma, which contained a part of the first exon of the SUPT4H1 gene." (PMID 27461012, 2016). "Prognostic genes include LAS1L, SUPT4H1, FAM72A, C11orf31 and MRPS22, which play key roles in the biological mechanisms of cancer." (PMID 33976726, 2021). "Best predicted cancer immunotherapy proteins with BC were RPS27, SUPT4H1, CLPSL2, POLR2K and RPL38, and the most altered ones were POLR2K, ASH2L, MED30, NSL1 and RPRD2." (PMID 32444848, 2020). "The best ranked cancer immunotherapy proteins related to BC were RPS27, SUPT4H1, and CLPSL2." (PMID 33537063, 2020).
SUPT4H1 also shares sentences with these, for which no sentence is quoted: infection (5 papers); neurological diseases (2); tumor (2); amyotrophic lateral sclerosis (1); autism (1); frontotemporal dementia (1); genetic disorders (1); neuropathic pain (1); spinocerebellar ataxia type 36 (1); viral infection (1).